GAB2 (GRB2 associated binding protein 2)
Diseases named in the same sentence as GAB2 in open-access papers (continued):
Sharing a sentence is not in itself a finding about the gene and the disease.
colorectal cancer (10 papers, 2016 to 2025). A primary or metastatic malignant neoplasm that affects the colon or rectum. "In previous study, we have identified Gab2 as miR-125b target gene that functions to mediate cell migration in colorectal cancer." (PMID 28881624, 2017). "Similar to VEGF, the expression of Gab2 in stage III–IV colorectal carcinoma was markedly increased than that of stage I–II tissues." (PMID 28420432, 2017). "Our results showed that elevated Gab2 induced colorectal carcinoma growth and vascularization through upregulation of VEGF expression mediated by ERK/c-Myc signaling pathway." (PMID 28420432, 2017). "To investigate the possible mechanism of Gab2 participating in cell metastasis of colorectal carcinoma, we examined its downstream effectors, AKT and ERK." (PMID 26754532, 2016). "The present study provides a novel fundamental insight into how Gab2 promotes metastasis in colorectal carcinoma." (PMID 26754532, 2016). "By controlling TAM.M2 polarization, GAB2 stimulates the growth of colorectal cancer." (PMID 40894221, 2025). "For example, miR-485 targeting of Gab2 inhibits tumor development in colorectal cancer." (PMID 36421826, 2022). "To find potential treatment for colorectal carcinoma with elevated Gab2 expression, we investigated whether U0126, an effective inhibitor of MEK, can suppress Gab2-induced tumor growth and angiogenesis." (PMID 28420432, 2017). "However, the role of Gab2 in the progression and metastasis of colorectal cancer (CRC) remains unclear." (PMID 26754532, 2016). "Our previous study has shown that Gab2 induces epithelial-to-mesenchymal transition (EMT) and promotes metastasis in colorectal cancer (CRC)." (PMID 28420432, 2017). "Taken together, our data demonstrated that overexpression of Gab2 contributed to MEK/ERK/c-Myc signaling–enhanced tumor growth and angiogenesis of human colorectal carcinoma through upregulating the levels of VEGF." (PMID 28420432, 2017). "To test the hypothesis that the commissioning of EMT by Gab2 is required for the activation of MEK/ERK signaling in colorectal carcinoma, we explore whether U0126, an effective MEK inhibitor, can inhibit Gab2-induced EMT and cell migration and invasion in CRC." (PMID 26754532, 2016). "Of further interest, we examined the possible pathway of Gab2 participating in cell metastasis of colorectal carcinoma and found that increased ERK1/2 phosphorylation in Gab2-upregulated CRC cells." (PMID 26754532, 2016).
acute myeloid leukemia (9 papers, 2009 to 2025). Acute myeloid leukemia (AML) is a group of neoplasms arising from precursor cells committed to the myeloid cell-line differentiation. "Using GAB2 deficient mice, we previously showed that GAB2 serves as an important effector of the oncogenic FLT3-ITD receptor tyrosine kinase in acute myeloid leukemia (AML) and of BCR::ABL1 in CML." (PMID 37161070, 2023). "The high frequent germline mutation in GAB2 was also present in acute myeloid leukemia in the International Cancer Genome Consortium study and in acute lymphoblastic leukemia with Ras-independent leukemogenic effects." (PMID 35033028, 2022). "The fact that c-Kit has been found mutated in numerous human malignancies, including acute myeloid leukemia, and that Gab2 is often overexpressed in acute myeloid leukemia suggests a potential role of Gab2-mediated PI3K activation in transformation." (PMID 22216034, 2012). "The chromosomal 11q13-14 locus containing the Gab2 gene is amplified in breast, ovarian, and gastric cancers and in acute myeloid leukemia (AML)." (PMID 23431498, 2013). "Gab2 is also important in the progression of other hematological neoplasias, such as juvenile myelomonocytic leukemia (JMML), acute myelocytic leukemia (AML), and acute lymphoblastic leukemia (ALL)." (PMID 23431498, 2013). "Amplification and/or over-expression of the human GAB2 gene has been also recently reported for ovarian and gastric cancer and acute myeloid leukemia (AML), although additional functional studies are required to dissect the role that Gab2 plays in these malignancies." (PMID 19737390, 2009).
glioma (8 papers, 2016 to 2026). A benign or malignant brain and spinal cord tumor that arises from glial cells (astrocytes, oligodendrocytes, ependymal cells). "For example, miR-302a is a tumor suppressor that restrains glioma cell proliferative, migrating, and invasive properties by targeting Grb2-associated binding protein 2 (GAB2)." (PMID 35181676, 2022). "miR-302a targeting of Gab2 inhibits the carcinogenesis of glioma cells." (PMID 36421826, 2022). "Interestingly, a recent study has shown that miR125a-5p could inhibit migration and invasion of glioma cells by mediating Gab2 to affect cytoskeleton rearrangement and MMPs expression." (PMID 26754532, 2016).
leukemia (8 papers, 2009 to 2025). A malignant (clonal) hematologic disorder, involving hematopoietic stem cells and characterized by the presence of primitive or atypical myeloid or lymphoid cells in the bone marrow and the blood. "Given its contribution to three oncogenic pathways, it is anticipated that GAB2 emerges as an important player in solid tumors and leukemia." (PMID 34903841, 2022). "We also summarize recent findings implicating Gab proteins, in particular the Gab2 isoform, in leukaemia, solid tumours and other human diseases." (PMID 19737390, 2009). "After the pivotal role of Gab2 in Bcr-Abl-mediated transformation had been established, its involvement in the pathogenesis of several other leukemias was discovered." (PMID 19737390, 2009). "Thus, blocking GAB2 might specifically impair leukemia cells with considerably less side effects than targeting its more ubiquitously expressed effectors PI3K and SHP2." (PMID 34903841, 2022). "Blocking GAB2 function or expression would be superior to targeting FLT3 directly, since the docking protein serves downstream of various leukemia-relevant RTKs." (PMID 34903841, 2022). "SHP2 and Gab2 have been demonstrated to be required for BCR/ABL-induced myeloid transformation and leukemia cell proliferation, suggesting that the Gab2-SHP2 axis is an important signaling event in leukemia." (PMID 26095858, 2015). "Employing the MAGeCK algorithm, this focused CRISPR screen unveiled COX4I1 (encoding Cytochrome c oxidase subunit 4 isoform 1) as a top essential gene in leukemia cells, alongside five previously reported leukemia essential genes (MYC, RPS6, CCND3, GAB2, and AURKB)." (PMID 39716856, 2025).
chronic myeloid leukemia (7 papers, 2013 to 2022). "In more specific terms, critical regulatory effect of Gab2 on SHP2 has been established by several studies and deregulation of this interaction is known to be associated with chronic myeloid leukemia (CML)." (PMID 25115405, 2014). "For example, Gab2 is an essential effector of Bcr-Abl in chronic myeloid leukemia (CML)." (PMID 34903841, 2022). "In “Chronic myeloid leukaemia”, we found that two lncRNAs (RP11–444D3.1 and RP11_326C3.2) are co–expressed with two different mRNAs (MYC and GAB2, respectively)." (PMID 32887470, 2020). "In another example, GAB2 has a regulatory role for PLCG2 in the osteoclast differentiation pathway, as well as an activating role in the chronic myeloid leukemia pathway." (PMID 31706268, 2019).
colitis (7 papers, 2019 to 2024). Inflammation of the colon. "It has been reported that the development of GAB2-induced colitis in mice is associated with increased T cell invasion." (PMID 38995439, 2024). "In contrast, epithelial-specific knockout of SHP-2, a Gab2 partner protein, causes barrier defects and colitis." (PMID 30936879, 2019). "Altogether, these results suggest that Gab2/3−/− mice are more susceptible to colitis development than WT mice." (PMID 30936879, 2019). "Susceptible recipients of Gab2/3−/− BM showed a colitis phenotype resulting in forced euthanasia due to body weight decreases ≥25%." (PMID 30936879, 2019). "Therefore, colitis resulting from Gab2/3 deficiency is hematopoietic cell-derived." (PMID 30936879, 2019). "Although Gab2/3−/− mice developed colitis-like phenotypes spontaneously, there was variation in controlling the rate of disease development as well as the severity of inflammation with age." (PMID 30936879, 2019). "The role of Gab2/3 in macrophages during colitis development was next assessed, where 1 × 106 LPS-polarized BMDMs from Gab2/3−/− or WT were adoptively transferred into Rag2−/− mice first, and then sorted naïve WT CD4+ T-cells were transferred 24 h later." (PMID 30936879, 2019). "We found that Gab2/3−/− T-cell phenotypes are most similar to the p110δ knockout mice that develop colitis." (PMID 30936879, 2019). "Furthermore, a recent study indicates that Gab family proteins Gab2/3 synergistically suppress colitis through controlling macrophage and CD8+ T cell activation." (PMID 36795486, 2023). "This indicates that Gab2/3−/− BMDMs were more potent at colitis induction than WT BMDMs." (PMID 30936879, 2019). "Future studies that target Gab1 in combination with Gab2/3 may shed light on the combined role of all Gabs in regulation of immune cell activation and colitis development." (PMID 30936879, 2019). "Mechanistic studies further defined that the cause of colitis was not due to deletion of Gab2/3 in colon epithelium but rather due to dysregulated immune cell biology." (PMID 30936879, 2019). "A fraction of these double knockout, but not single knockout, mice developed rectal prolapses and suffered from diarrheas driven by macrophages and predominately CD8+ T-cells, supporting a novel major redundant role for Gab2/3 in immune cell inactivation required for the suppression of colitis." (PMID 30936879, 2019). "CD8+ T-cell profiling predicts prognosis in patients with Crohn's disease and ulcerative colitis and we observed the main contribution to colitis development was mediated by cytokine producing, proliferative, CD8+ Gab2/3−/− T-cells in the intraepithelial compartment." (PMID 30936879, 2019). "GRB2 associated binding protein 2/3 (Gab2/3) double knockout mice could develop spontaneous colitis with rectal prolapse and diarrhea, mainly involving macrophages and CD8+ T cells, which was due to the role of Gab2/3 in suppressing the inactivation of immune cells in the process of inflammation." (PMID 33535181, 2021). "Gab2/3−/− mice, but not single knockout mice, developed spontaneous colitis." (PMID 30936879, 2019). "However, it was recently suggested that GAB2 and GAB3 may perform redundant functions in immune cells, given that Gab2/3−/− mice exhibit T cell- and macrophage-mediated colitis whereas Gab2−/− and Gab3−/− mice do not." (PMID 33763075, 2021). "Interestingly, given the important role for IL-17/IL-23 signaling in colitis, the observed increase in Tc17 cells lacking Gab2/3 provides new insights toward not only Gab2/3 regulation downstream of cytokines but also in regulation of important cytokine producing cells." (PMID 30936879, 2019).
hepatocellular carcinoma (7 papers, 2017 to 2024). A malignant tumor that arises from hepatocytes. "In hepatocellular carcinoma, miR-663b was found to target Gab2 to inhibit cell proliferation and invasion." (PMID 36421826, 2022). "Next, we assessed the effects of miRNAs on the biological function of Gab2 in hepatocellular carcinoma cells." (PMID 36421826, 2022). "Negative regulations of NIMA-related kinase 2 (NEK2) in hepatocellular carcinoma and a repression of GRB2-associated-binding protein 2 (GAB2) in nonsmall cell lung cancer have been reported." (PMID 33298968, 2020). "Compared with a faint expression in para-carcinoma tissue, Gab2 was highly expressed in ∼60–70% of human hepatocellular carcinoma (HCC) specimens." (PMID 28842424, 2017). "Transwell migration assay indicated that hepatoma cell migration was enhanced by Gab2 overexpression but inhibited by Gab2 deletion (purple cells)." (PMID 28842424, 2017). "Statistical analysis indicated that Gab2 deletion significantly decreased the number of positive cells for Ki-67 and pH3, which indicated that Gab2 mediates the growth of hepatic carcinoma." (PMID 28842424, 2017). "In addition, we also checked the expression of Gab2 and selected miRNAs in another hepatocellular carcinoma cell line, SMMC-7721, and confirmed the opposite pattern of expression between Gab2 and these miRNAs (miR-9, miR-181a, and miR-34a)." (PMID 36421826, 2022). "In addition, the Jak2 inhibitor, AG490, markedly restrained the ability of Gab2 to promote hepatoma cell proliferation and metastasis." (PMID 28842424, 2017). "Of importance, we found that Jak2 was a key interactant of Gab2 in hepatoma cells." (PMID 28842424, 2017). "Here, we screened for and identified two miRNAs that target Gab2 to suppress the proliferation and migration of hepatocellular carcinoma (HCC) cells." (PMID 36421826, 2022). "Because the expression and function of Gab2 and miRNAs in different hepatocellular carcinoma cell lines are inconsistent, more studies in different HCC cell lines would perfect the understanding of the relationships between Gab2 and miR-181a and miR-9." (PMID 36421826, 2022).
gastric cancer (6 papers, 2009 to 2024). A primary or metastatic malignant neoplasm involving the stomach. "Gab2 overexpression is also a clinically significant biomarker for malignant invasion and metastasis of several cancers, including breast and gastric cancer." (PMID 30936879, 2019).
lung cancer (6 papers, 2015 to 2024). A malignant neoplasm involving the lung. "Gab2 is overexpressed in malignant lung tissues, compared with normal lung tissues, suggesting Gab2 has a novel role in the development of lung cancer." (PMID 26095858, 2015). "In addition, a previous study reported that Gab2 positively regulates mucin synthesis and goblet cell hyperplasia through an IL-13-mediated TYK2/STAT6 pathway in lung cancer and chronic obstructive pulmonary disease." (PMID 26095858, 2015).
acral melanoma (4 papers, 2022 to 2025). "Amplifications of PAK1 and GAB2 were more commonly observed in acral melanomas, whereas SF3B1 R625 codon mutations were unique to mucosal melanomas (12.9%)." (PMID 35706047, 2022). "BRAF and NRAS mutations are common in acral melanocytic nevus, whereas acral melanoma shows lower rates of KIT, NF1, BRAF, and NRAS mutations and remarkable copy number variations in genes such as CCND1, CDK4, hTERT, PAK1, and GAB2." (PMID 35997352, 2022). "Identified CNVs in acral melanoma have implicated several genes, including CCND1, CDK4, hTERT, PAK1, GAB2, EP300, YAP1, and MDM2." (PMID 35997352, 2022).
breast tumors (4 papers, 2014 to 2019). "Shp2, in cooperation with GRB2-associated binding protein 2 (Gab2), increases the proliferation of human breast epithelial MCF10A cells and enhances the metastasis of Her2/Neu-induced breast tumors in the transgenic mouse model." (PMID 25048202, 2014). "Agents that interact with the Gab2 or Gab2-mediated pathways may be useful for treating breast tumors overexpressing Gab2 and/or HER2." (PMID 26095858, 2015).
Hepatic steatosis (4 papers, 2017 to 2023). Steatosis is a term used to denote lipid accumulation within hepatocytes. "Our previous studies have found that Growth factor receptor-bound protein 2–associated binding protein 2 (Gab2)—a docking protein—governs the development of fatty liver disease." (PMID 28842424, 2017). "Our previous experiment discovered that Gab2 mediated the lipid metabolism in fatty liver disease and Gab2 deficiency prevented the lipid accumulation in the liver, indicating that Gab2 may be involved in obesity." (PMID 33637697, 2021). "Furthermore, it has been proved that the cause of fatty liver disease can stimulate the expression of Gab2, which mediate the biosynthesis of lipids in the liver of mice." (PMID 33637697, 2021). "Our previous studies have demonstrated that the ERK, PI3K-Akt, and Socs3-Stat3 pathways are involved in the Gab2 regulatory network in fatty liver pathogenesis." (PMID 28842424, 2017). "Our previous study demonstrated that Gab2 recruited PI3K/Akt, suppressor of cytokine signaling 3 (Socs3)/Stat3, and other signaling molecules in fatty liver induced by pathologic factors." (PMID 28842424, 2017).
non-small cell lung carcinoma (4 papers, 2020 to 2024). A group of at least three distinct histological types of lung cancer, including non-small cell squamous cell carcinoma, adenocarcinoma, and large cell carcinoma. "Non-small cell lung cancer has GAB2 and PIK3R1 as two upregulated genes." (PMID 34764329, 2021).
prostate carcinoma (4 papers, 2020 to 2024). A carcinoma that arises from epithelial cells of the prostate gland. "miR-218b targeting of Gab2 mediates the tumorigenesis in prostate cancer through the PI3K/AKT/GSK-3β pathway." (PMID 36421826, 2022). "In human prostate cancer, the use of gene chip technology to explore the role of GAB2 in human prostate cancer cells provides a new therapeutic target for prostate cancer." (PMID 34326892, 2021).
Allergy (3 papers, 2016 to 2022). An allergy is an immune response or reaction to substances that are usually not harmful. "As a result, Syk and Gab2 are promising targets for the development of allergy medicines." (PMID 34836105, 2021). "Hence, targeting the vesicle trafficking machinery and/or downregulation of Gab2 might represent conceivable mechanisms by which PBMCsec inhibits FcεR signalling and immune cell activation in the allergy context." (PMID 35671621, 2022). "Increasing reports have demonstrated that Gab2/PI3-K/Akt and Fyn/Syk pathway plays an essential role in the development of allergic diseases." (PMID 27200102, 2016).
intestinal tumor (3 papers, 2016 to 2020). "The results from our study suggest that Gab2 promotes intestinal tumor growth and angiogenesis through upregulation of VEGF expression mediated by the MEK/ERK/c-Myc pathway." (PMID 28420432, 2017). "Our work highlights that Gab2 induces EMT through the MEK/ERK/MMP pathway, which in turn promotes intestinal tumor metastasis." (PMID 26754532, 2016).
mucosal melanoma (3 papers, 2022 to 2025). A melanoma that arises from a mucosal site. "In addition to sharing similar recurrently affected genes, acral and mucosal melanomas also shared the most recurrently altered TAD boundary (chr11:77750000–77825000), which is adjacent to the TADs containing PAK1 and GAB2." (PMID 38758740, 2024).